RASD1 (ras related dexamethasone induced 1)
Description:
Small GTPase. Negatively regulates the transcription regulation activity of the APBB1/FE65-APP complex via its interaction with APBB1/FE65 (By similarity).
Synonyms: AGS1; DEXRAS1; MGC:26290
Tractability: Antibody: UniProt places it where antibodies can reach, with high confidence; its Gene Ontology location is reachable by antibodies, with medium confidence; the Human Protein Atlas places it where antibodies can reach.
Gene: Protein-coding gene on chromosome 17 (17,494,437 to 17,496,396, reverse strand). Ensembl gene ENSG00000108551.
Subcellular location: Cell membrane; Cytoplasm, perinuclear region; Nucleus
Subcellular location (Human Protein Atlas): Nucleoplasm; Plasma membrane
Gene Ontology:
Molecular function: protein binding; G-protein beta-subunit binding; GTPase activity; GTP binding
Biological process: G protein-coupled receptor signaling pathway; signal transduction; cellular response to nitric oxide; intracellular signaling cassette; negative regulation of DNA-templated transcription; NMDA selective glutamate receptor signaling pathway
Cellular component: cytoplasm; nucleus; perinuclear region of cytoplasm; plasma membrane; sarcoplasmic reticulum
Genetic constraint (gnomAD): Loss-of-function variants: 13 observed, 16.07 expected, observed/expected ratio (o/e) 0.81, 90% interval 0.53 to 1.29. The upper end of that interval is the gene's LOEUF score, 1.29, which puts it in group 5 of 6, group 1 being the genes least tolerant of losing a copy. Missense variants: 397 observed, 416.92 expected, observed/expected ratio (o/e) 0.95, 90% interval 0.88 to 1.03. Synonymous variants: 170 observed, 176 expected, observed/expected ratio (o/e) 0.97, 90% interval 0.85 to 1.1.
Homologues: Orthologues: chimpanzee RASD1 (100% identical), macaque RASD1 (99% identical), mouse Rasd1 (98% identical), guinea pig RASD1 (97% identical), rat Rasd1 (97% identical), dog RASD1 (97% identical), rabbit RASD1 (91% identical), pig RASD1 (86% identical), tropical clawed frog rasd1 (81% identical). Paralogues in human: RASD2 (60% identical), DIRAS1 (28% identical), DIRAS2 (27% identical), RAP2B (26% identical), RAP2C (26% identical), RAP2A (25% identical), KRAS (24% identical), RRAS2 (24% identical), RAP1A (24% identical), RRAS (24% identical), HRAS (23% identical), RAP1B (23% identical), and 23 more.
Diseases named in the same sentence as RASD1 in open-access papers:
RASD1 is named in the same sentence as 98 diseases in open-access papers, as found by Europe PMC text mining. Sharing a sentence is not in itself a finding about the gene and the disease. The quoted sentences say what the papers report.
breast carcinoma (15 papers, 2011 to 2025). "In breast cancer, RASD1 has been implicated in apoptosis regulation via the mitochondrial pathway, where its upregulation induces apoptotic cell death." (PMID 40362656, 2025). "Notably, our analysis revealed reduced RASD1 mRNA levels in breast cancer tissues, suggesting a potential loss of its apoptotic regulatory function in tumorigenesis." (PMID 40362656, 2025). "The involvement in known cancer pathways and its experimental validation as a direct target of hsa-miR-375 makes RASD1 a promising candidate for further evaluation and underlines the potential biological significance of hsa-miR-375 in early stage breast cancer." (PMID 26962366, 2016). "In breast cancer, RASD1 shows low transcript levels alongside high protein expression, indicating enhanced protein stability or translational regulation." (PMID 40362656, 2025). "RASD1 is involved in the apoptosis of prostate cancer cells treated with an anti-cancer drug, formononetin and in breast cancer cells treated with calycosin." (PMID 35052372, 2021). "During the induction of apoptosis by different agents in cancer cells, RASD1 is upregulated, and RASD1 expression predicts local control in early breast cancer patients and better survival in astrocytoma patients." (PMID 34830961, 2021). "Taken together, the current analysis is the first clinical verification of experimental data on hsa-miR-375 combined with RASD1 in breast cancer." (PMID 33255991, 2020). "The current two-phase study demonstrates that hsa-miR-375/RASD1 signaling is able to predict local control in early breast cancer." (PMID 33255991, 2020). "This is the first study that corroborates preclinical data on hsa-miR-375/RASD1 signaling for LC in breast cancer patients." (PMID 33255991, 2020). "Fifteen targets were predicted both in Target Scan (Release 6.2) and PITA (Venn diagram in Figure A1) including RASD1, which is a validated functional target of hsa-miR-375 in breast cancer cells." (PMID 33255991, 2020). "Among these, we identified one gene that has been validated experimentally by reporter gene assay in breast cancer cells: RASD1." (PMID 26962366, 2016). "miR-375 was also upregulated in estrogen receptor alpha- (ERα-) positive breast cancer cell lines, which promoted cell proliferation and induced ERα upregulation via RASD1, a negative regulator of ERα." (PMID 25404787, 2014). "Loss of miR-375 has also been reported in gastric, liver and breast cancers, and a putative tumor suppressor role has been linked to a failure to repress the oncogenic miR-375 targets JAK2, YAP, PDK1 and RASD1." (PMID 22132151, 2011). "Moreover, it has been demonstrated that RASD1 can inhibit the proliferation and induce the apoptosis of breast cancer cells, lung cancer cells, and prostate cancer cells and suppress the migration and invasion of glioma cells." (PMID 38902717, 2024). "The aim of the current two-phase study was to investigate whether hsa-miR-375-signaling through RASD1 could predict local control (LC) in early breast cancer." (PMID 33255991, 2020). "In summary, the current study demonstrates that hsa-miR-375/RASD1 signaling may contribute to predict local control after BCT for early stage breast cancer." (PMID 33255991, 2020). "Moreover, hsa-miR-375/RASD1 signaling may serve as a predictive marker for local relapse in early breast cancer." (PMID 40362656, 2025). "Moreover, a similar suppression of cell growth by RASD1 was also observed in breast cancer cells." (PMID 28600528, 2017). "It has been shown that miR-375 suppresses Ras dexamethasone-induced 1 (RASD1) as its potential target, and RASD1 can suppress the growth of breast cancer cells and down-regulate ERα expression." (PMID 23056006, 2012). "To date, only one study in a smaller cohort than ours investigated miRs and LC in breast cancer, whereas none considered the role of RASD1, let alone the hsa-miR-375/RASD1 combination." (PMID 33255991, 2020).
breast carcinoma (continued). "The same treatment did not affect miR-375 or RASD1 expression in the ER− MDA-MB-468 or SKBR3 breast cancer cells or in the MCF10A cells." (PMID 29096683, 2017). "Results from our previous study suggest that calycosin inhibits the proliferation of ER+ breast cancer cells and that miR-375, RAS dexamethasone-induced 1 (RASD1), and ER may be involved in this process." (PMID 29096683, 2017).
glioma (9 papers, 2017 to 2025). A benign or malignant brain and spinal cord tumor that arises from glial cells (astrocytes, oligodendrocytes, ependymal cells). "For instance, RASD1 suppresses cell growth in a lung cancer cell line and inhibits glioma invasion and migration by inactivating the AKT/mammalian target of rapamycin (mTOR) pathways." (PMID 40362656, 2025). "In patients with KIRC, low grade glioma (LGG), and PAAD, high RASD1 expression is associated with prolonged survival." (PMID 40362656, 2025). "In glioma, RASD1 has been demonstrated to act as a tumor suppressor, with overexpression inhibiting tumor invasion and progression." (PMID 40362656, 2025). "Aberrant expression of RASD1 has been observed in several malignancies, including osteosarcoma, prostate cancer, renal cell carcinoma, and glioma." (PMID 38902717, 2024). "Thirdly, we set up an intracranial glioma xenograft model in nude mice to observe the effects of RASD1 overexpression on tumor growth and expansion in vivo." (PMID 28600528, 2017). "Secondly, we screened the glioma cells to reveal the changes in some important signaling pathways by RASD1 overexpression." (PMID 28600528, 2017). "This in vivo evidence further supported an inhibitory effect of RASD1 overexpression on glioma cell invasion." (PMID 28600528, 2017). "We explored the candidate mechanisms in Lenti-RASD1 glioma cells by an intracellular signaling array that can simultaneously reflect several important signaling cascades, e.g., MAPK, mTOR, and AKT." (PMID 28600528, 2017). "In the present study, we first established stable glioma cells by overexpressing RASD1 lentivirus plasmid and then investigated the effects of overexpressing RASD1 on the proliferation, migration, and invasion of glioma cells." (PMID 28600528, 2017). "An intracranial glioma xenograft model was established in nude mice to investigate the effect of RASD1 overexpression on glioma growth and expansion in vivo." (PMID 28600528, 2017). "An intracellular signaling array revealed that the phosphorylation of both AKT and the S6 ribosomal protein significantly decreased with RASD1 overexpression in glioma cells." (PMID 28600528, 2017). "We used the transwell assay in the presence of Matrigel to observe the effects of RASD1 overexpression on glioma cell invasion." (PMID 28600528, 2017). "These clinical data suggested the potential involvement of RASD1 in the progression of human glioma." (PMID 28600528, 2017). "We therefore used wound healing assays to observe the effects of overexpressing RASD1 on glioma cell migration." (PMID 28600528, 2017). "In line with these in vitro results, overexpressing RASD1 markedly suppressed glioma expansion in the intracranial glioma xenograft model." (PMID 28600528, 2017). "Taken together, these findings suggested that the overexpression of RASD1 inhibited glioma cell migration and invasion." (PMID 28600528, 2017). "Interestingly, we observed the upregulation of RASD1, a gene that inhibits glioma cell migration and invasion by deactivating the AKT/mTOR signaling pathway." (PMID 39874307, 2025). "Previous in vitro studies have demonstrated that RASD1 possesses tumor-suppressive potential, such as limiting colony formation, migration, and invasion, in various cancers, including in lung, prostate, breast, gastric cancer and glioma." (PMID 40362656, 2025). "Overexpression of RASD1 inhibited glioma expansion and inactivated the AKT/mTOR pathway." (PMID 33706799, 2021). "Interestingly, we found that the overexpression of RASD1 significantly inhibited both the migration and invasion abilities of glioma cells." (PMID 28600528, 2017). "Additionally, we found no significant alterations of p-ERK1/2, p-JNK1/2 and p-P38 in RASD1-overexpressing glioma cells by antibody array, which paralleled the insignificant effects of RASD1 overexpression on glioma cell proliferation." (PMID 28600528, 2017).
glioma (continued). "To explore the candidate mechanisms by which RASD1 exerted its effect on glioma cell migration and invasion, we performed an intracellular signaling array that included 18 important signaling molecules with phosphorylation or cleavage in stable RASD1-overexpressing glioma cells." (PMID 28600528, 2017). "However, the overexpression of RASD1 inhibited glioma cell migration and invasion." (PMID 28600528, 2017). "Therefore, RASD1 may serve as an attractive target for the development of novel diagnostic, prognostic and therapeutic approaches to glioma management." (PMID 28600528, 2017). "However, the role and mechanism of RASD1 in the progression of human glioma remain largely unknown." (PMID 28600528, 2017). "We found that the overexpression of RASD1 remarkably suppressed the phosphorylation of AKT (Thr308), GSK3β and S6 ribosome protein in glioma cells." (PMID 28600528, 2017). "In conclusion, both in vitro and in vivo findings suggest that RASD1 may play an inhibitory role in cell migration and invasion in brain glioma, although the loss of function data are lacking due to low expression of the RASD1 protein in the glioma cell lines studied." (PMID 28600528, 2017). "In our study, overexpressing RASD1 had no significant influence on the proliferation of glioma cells, as determined by CCK8, EdU and colony formation assays." (PMID 28600528, 2017). "In the present study, we demonstrated that the overexpression of RASD1 significantly inhibited the migration and invasion of glioma cells, without affecting cell proliferation." (PMID 28600528, 2017). "Notably, colorectal cancers exhibited high protein expression, while lymphomas, gliomas, and pancreatic cancer displayed low to no protein expression of RASD1." (PMID 40362656, 2025). "Notably, RASD1 protein expression was detected in about 80% of colorectal cancer patients, whereas it was largely absent in patients with lymphoma and glioma according to data from the Human Protein Atlas." (PMID 40362656, 2025). "The protein levels of RASD1 increased in grade II (P = 0.005, n = 11) and grade III (P = 0.001, n = 11) astrocytoma tissues compared to nontumor brain tissues (n = 9), with no significant changes in the grade IV glioma tissues (P = 0.179, n = 11)." (PMID 28600528, 2017).
osteosarcoma (8 papers, 2012 to 2024). A usually aggressive malignant bone-forming mesenchymal neoplasm, predominantly affecting adolescents and young adults. "Of note, overexpression of genes belonging to the amplified region (COPS3, PMP22, GID4, ARGHAP44, TOP3A, SHMT1, and RASD1) was studied in osteosarcoma cell lines." (PMID 35920001, 2022). "This would make RASD1 a poor candidate oncogene for osteosarcoma tumourigenesis, However, in accordance with an oncogenic function, knockdown of the expression of RABB27A, encoding another member of the Ras superfamily, was shown to inhibit the growth of melanoma cells." (PMID 22292074, 2012). "Based on our statistical analysis of the correlation between copy number increase and expression level for each of the top ranking genes, we identified RICH2, c17orf45, TOP3A, COPS3, SHMT1, PRPSAP2, PMP22, and RASD1 as candidate osteosarcoma oncogenes in the 17p11.2-p12 region." (PMID 22292074, 2012). "However, prognostic studies for the other candidate genes require the development of new antibodies (C17orf39, RICH2, RASD1) or testing of available antibodies on osteosarcoma tissues (TOP3A, COPS3, SHMT1, PRPSAP2, PMP22), which is presently underway." (PMID 22292074, 2012).
coronary artery disease (4 papers, 2017 to 2023). "Additional studies are required to further characterize the role of Rasd1 in coronary heart diseases." (PMID 35938163, 2022).
gastric cancer (4 papers, 2022 to 2025). A primary or metastatic malignant neoplasm involving the stomach. "Our findings support this observation by showing low RASD1 mRNA levels in stomach cancer tissues." (PMID 40362656, 2025). "Similarly, in gastric cancer, KIAA1429, a regulatory subunit of the m6A methyltransferase complex, promotes tumor growth and metastasis by destabilizing RASD1 mRNA through an m6A-YTHDF2-dependent mechanism." (PMID 40362656, 2025).
lung carcinoma (4 papers, 2016 to 2024). "The potential function of RASD1 was investigated in breast and lung cancer cells as well as a xenograft model." (PMID 33255991, 2020). "An overexpression of RASD1 seems to increase apoptosis via mitochondrial apoptosis pathway in prostate, breast, and lung cancer cell lines." (PMID 27902465, 2016).
pancreatic cancer (4 papers, 2012 to 2025). "This range in RASD1 expression likely stems from inherent genetic and molecular distinctions characteristic of each specific cancer type, as well as the heterogeneity of tumors like pancreatic cancer, renal cancer, and glioblastoma." (PMID 40362656, 2025). "Genes that were upregulated in low-MUC1 PDA samples (MAPK12, RASD1, and AMH) were found to be favorable for OS in pancreatic cancer (Human protein atlas)." (PMID 35237602, 2022). "Similarly to the expression in tumor samples, RASD1 is expressed in most colorectal cancer cell lines and is either not present or is expressed in low levels in most brain, pancreatic cancer, and lymphoma cell lines." (PMID 40362656, 2025).
prostate carcinoma (4 papers, 2012 to 2024). A carcinoma that arises from epithelial cells of the prostate gland. "RASD1 could thus play a tumor suppressor role in prostate cancer cells." (PMID 34830961, 2021).
viral infection (4 papers, 2016 to 2023). "Not surprisingly, cell cycle, viral genes, and host cell genes correlating with viral infection, such as RASD1, appeared as the strongest gene expression markers." (PMID 31653857, 2019). "Interestingly genes RASD1 NEFL, CALCA and PIK3R5 are more involved in cell signalling and proliferation, possibly reflecting the impact of viral infection on cell-cycle." (PMID 28406989, 2017).
Cognitive impairment (3 papers, 2021 to 2024). Abnormal cognition is characterized by deficits in thinking, reasoning, or remembering. "Besides, our in vivo results found Rasd1 deficiency abated the neurological deficits, cognitive impairments, glia activation, neuroinflammatory response, and oxidative stress due to SAH." (PMID 37735980, 2024). "Prior research has elicited the functionality of RASD1 as a pivotal regulator in cognitive deficits." (PMID 33982674, 2021). "Ferroptosis may also be involved in cognitive impairment caused by sevoflurane in the developing brain, which may be related to activation of N-methyl-D-aspartate receptor (NMDAR)-RASD1(Ras-related dexamethasone-induced 1) signaling." (PMID 34766256, 2022).
multiple myeloma (3 papers, 2018 to 2026). "For instance, RASSF1A and RASD1 promoter DNA methylation have been shown in myeloma to be associated with activation of RAS signalling." (PMID 30201956, 2018). "Moreover, methylation of RASSF1A and RASD1 was associated with low expression in human myeloma cell lines, thereby demonstrating methylation-mediated gene silencing." (PMID 30201956, 2018). "Herein, we showed tumour-specific methylation of both RASSF1A and RASD1 in myeloma cell lines, as evidenced by the presence of methylated MSP signals in myeloma cell lines but not normal control DNA." (PMID 30201956, 2018). "Indeed, in a genome-wide methylation study of 115 primary myeloma samples using Illumina 27 K28, RASD1 methylation was inversely correlated with expression, hence further testifying the role of methylation-mediated silencing for RASD1 in myeloma patients." (PMID 30201956, 2018). "In addition, RASD1 modulates the development of dexamethasone resistance in multiple myeloma." (PMID 38902717, 2024).
pancreatic adenocarcinoma (3 papers, 2022 to 2025). "Therefore, in an exploratory manner, we aimed to further investigate this correlation and explore whether RASD1 expression in KIRC, LGG, and pancreatic adenocarcinoma (PAAD) is related to changes in the tumor microenvironment." (PMID 40362656, 2025).
thyroid cancer (3 papers, 2020 to 2025). "We observed significantly lower promoter methylation levels of RASD1 in colon adenocarcinoma (COAD), esophageal carcinoma (ESCA), head and neck squamous cell carcinoma (HNSC), KIRC, LIHC, prostate adenocarcinoma (PRAD), READ, thyroid carcinoma (THCA), and UCEC compared to normal tissues." (PMID 40362656, 2025).